GPRASP1 (G protein-coupled receptor associated sorting protein 1)
Description:
Modulates lysosomal sorting and functional down-regulation of a variety of G protein-coupled receptors. Targets receptors for degradation in lysosomes via its interaction with BECN2.
Synonyms: GASP-1; GASP; GASP1
Tractability: PROTAC: ubiquitination databases record sites on it; its protein half-life has been measured.
Gene: Protein-coding gene on chromosome X (102,650,345 to 102,659,083, forward strand). Ensembl gene ENSG00000198932.
Subcellular location: Cytoplasm
Subcellular location (Human Protein Atlas): Cytosol
Gene Ontology:
Molecular function: protein binding
Biological process: endosome to lysosome transport; G protein-coupled receptor catabolic process
Cellular component: cytosol; nucleus; cytoplasm
Homologues: Orthologues: chimpanzee GPRASP1 (99% identical), macaque GPRASP1 (95% identical), pig GPRASP1 (69% identical), dog GPRASP1 (68% identical), rabbit GPRASP1 (67% identical), mouse Gprasp1 (58% identical), rat Gprasp1 (57% identical), zebrafish armc10 (5% identical), tropical clawed frog armc10 (4% identical), Caenorhabditis elegans Y67A10A.7 (4% identical). Paralogues in human: GPRASP2 (35% identical), ARMCX4 (23% identical), GPRASP3 (13% identical), ARMCX5 (12% identical), ARMCX2 (8% identical), ARMCX3 (7% identical), ARMCX1 (7% identical), ARMC10 (6% identical), ARMCX6 (4% identical), ARMC12 (4% identical).
Diseases named in the same sentence as GPRASP1 in open-access papers:
GPRASP1 is named in the same sentence as 12 diseases in open-access papers, as found by Europe PMC text mining. Sharing a sentence is not in itself a finding about the gene and the disease. The quoted sentences say what the papers report.
glioblastoma (3 papers, 2022 to 2024). The most malignant astrocytic tumor (WHO grade IV). "Among these genes, GPRASP1 was correlated to the prognosis of glioblastoma patients." (PMID 37237274, 2023). "in 2021 found that the prognosis of glioblastoma (GBM) can be determined by seven differentially expressed genes (DEGs) 47, namely CLEC5A, HOXC6, HOXA5, CCL2, GPRASP1, BSCL2, and PTX3." (PMID 39132508, 2024).
breast carcinoma (2 papers, 2022). "GPRASP1 has been found overexpressed in brain, pancreatic, and breast cancers as compared to their respective normal tissues, and it may be a biomarker for early-stage cancer." (PMID 35203526, 2022). "In breast cancer, eight winning TFs (ZBTB16, KLF2, KLF4, NR2F1, EGR1, FOSB, EPAS1, and GPRASP1) can form a coregulatory network, and three other winning TFs (MYBL2, FOXM1, and TAL1) can form another coregulatory network." (PMID 36101460, 2022).
lung carcinoma (2 papers, 2022). "G protein coupled receptor-associated sorting protein 1 (GPRASP1) has been reported to be aberrantly expressed in several cancer types, including liver, breast, brain, and lung cancers, and may serve as a potential tumor biomarker for patients." (PMID 35479956, 2022).
Cognitive impairment (1 paper, 2022). Abnormal cognition is characterized by deficits in thinking, reasoning, or remembering. "While the role of GPRASP1 on gene transcription is unknown, BCL11A haploinsufficiency has been associated with cognitive impairments." (PMID 36523271, 2022).
thyroid cancer (1 paper, 2023). "The aim of this study was to assess the potential of G-protein coupled receptor-associated sorting protein 1 (GASP-1) as a valid thyroid cancer biomarker." (PMID 37444514, 2023).
thyroid neoplasms (1 paper, 2023). "In the current study, we analyzed the involvement of G-protein coupled receptor-associated sorting protein 1 (GASP-1) in the development and progression of thyroid neoplasms." (PMID 37444514, 2023).
X-linked intellectual disability (1 paper, 2015). An X-linked intellectual deficiency in which not enough information is known, reported or published to indicate whether a gene causes non-syndromic or syndromic presentations. "In addition, Gdi1 and Syp have been implicated in X-linked intellectual disability in humans, and Gprasp1 mutations are associated with striatum-dependent behavior inhibition." (PMID 25785854, 2015).
cancer (5 papers, 2022 to 2024). A tumor composed of atypical neoplastic, often pleomorphic cells that invade other tissues. "We have previously identified that G-protein-coupled receptor-associated sorting protein 1 (GASP-1) is a ubiquitous tumor marker that is required for cancer progression and invasion." (PMID 39518097, 2024). "GPRASP1 (G protein coupled receptor-associated sorting protein 1) is deregulated in several types of cancer, and its downregulation is related to the inhibition of the Tachykinin Receptor family, which is involved in inflammation and cancer cell proliferation." (PMID 36661515, 2023). "Consistent with results obtained from the TCGA-COAD cohort, six CRGs, including DPP7, GPRASP1, UNC5C, RAB3B, PCDH9, SLC18A2, were significantly downregulated, whereas CDR2L was upregulated in cancer tissues in comparison with paracancerous normal tissues." (PMID 37384293, 2023).
tumor (4 papers, 2022 to 2023). "SPINK1, FABP4, and MMP10 showed darker staining in tumor tissues, and GPRASP1, CLCA4, and LAMP5 showed lighter staining." (PMID 35479956, 2022). "DPP7, CDR2L exhibited higher and UNC5C, RAB3B, SLC18A2, GPRASP1, PCDH9 exhibited lower expression in tumor tissues (P<0.05)." (PMID 37384293, 2023). "We found that most genes with hazard ratio > 1 (GPRASP1, APLP1, ALPK3, SPTBN5, PCDHB14, LZTS3 and RGL2) have a higher expression in tumor tissues than normal tissues except LINGO1 and LZTS1." (PMID 37237274, 2023). "Protein level of tumor promoting genes (GPRASP1, APLP1, ALPK3, SPTBN5, PCDHB14, LZTS3, RGL2) were higher in tumor tissues." (PMID 37237274, 2023).
GPRASP1 also shares sentences with these, for which no sentence is quoted: benign prostatic hyperplasia (1 paper); head and neck cancer (1); prostate carcinoma (1).